EGFR (epidermal growth factor receptor)
Diseases named in the same sentence as EGFR in open-access papers (continued):
Sharing a sentence is not in itself a finding about the gene and the disease.
breast carcinoma (continued). "To investigate the effects of GD3S expression on EGFR signaling pathways, we examined EGFR protein levels and downstream signaling in GD3S-expressing breast CSCs and breast cancer cell lines by immunoblotting." (PMID 28537895, 2017). "The interdependent down-regulation of EGFR, CD44 and EMMPRIN in the three breast carcinoma cell lines attenuated the invasion tendency, as demonstrated by the scratch test and zymography although this effect was less evident in MDA-MB-231 cells." (PMID 28465354, 2017). "At the surface of the cancer cells, ErbB proteins are regularly overexpressed: at about two millions of EGFR in A-431 human epidermoid carcinoma cells and 105-106 ErbB2 proteins in SK-BR-3 breast cancer cell line." (PMID 28286519, 2017). "Lapatinib, a small molecule ErbB2/EGFR inhibitor, is FDA-approved for the treatment of metastatic ErbB2-overexpressing breast cancer; however, lapatinib resistance is an emerging clinical challenge." (PMID 28938602, 2017). "We have recently described that luminal breast cancer cells widely express MUC1 and exhibit a low level of EGFR in situ, whereas triple-negative breast cancer cells are negative for MUC1 and positive for EGFR21." (PMID 28775276, 2017). "Mechanistically, we identified PHD2 as a direct binding partner of EGFR and show that PHD2 regulates EGFR stability as well as its subsequent signaling in breast carcinoma cells." (PMID 28038470, 2017). "EGFR protein expression and phosphorylation were also downregulated by AZD4547, suggesting a connection between the EGFR and FGFR families of RTKs in ErbB2-overexpressing breast cancers." (PMID 28900173, 2017). "For instance, TGF-β1 induces EMT by the transactivation of EGFR/EGF signaling through HA/CD44 in lung and breast cancer cells." (PMID 29261154, 2017). "For example, cetuximab and panitumumab target epidermal growth factor receptor (EGFR) to treat colorectal cancer, trastuzumab targets HER2 to treat breast cancer, and rituximab targets CD20 to treat leucocythemia." (PMID 28440691, 2017). "A similar effect was observed in breast cancer when E2F1, TGFBR2, and EGFR are simultaneously active." (PMID 28775339, 2017). "We evaluated EGFR, HER2, c-MYC, and MET gene status by determining the degree of amplification, GCN gain and the 2013 ASCO/CAP HER2 testing guideline criterion for breast cancer." (PMID 28764718, 2017). "We found a significant correlation between %mac and EGFR phosphorylation in LIM1215 colorectal tumour xenograft, which further corroborates our finding in HCC1954 breast cancer model." (PMID 28166195, 2017). "Lapatinib (Tykerb®), an EGFR/HER2 dual inhibitor, is clinically used for patients with HER2 positive breast cancer, and the senescence-related effect of lapatinib has been explored in breast cancer cells." (PMID 28841181, 2017). "Likewise, resistance to anti-EGFR and anti-HER2 therapies are associated with PI3K pathway activation by PIK3CA mutations in EGFR mutant LADC, and HER2-positive breast cancer, or by loss of PTEN or HER3 activation (which activates the PI3K pathway) in breast cancer models." (PMID 29156674, 2017). "In breast cancer, NTSR1-induced activation of EGFR and HER2 receptors rendered these cancers aggressive, yet highly responsive to lapatinib and metformin in mice." (PMID 28316623, 2017). "The main aim of this study was to assess the mechanism between the dimerization of EGFR and HER2 and motility of breast cancer." (PMID 28881584, 2017). "Lapatinib (Tykerb), a small molecule tyrosine kinase inhibitor which targets both epidermal growth factor receptor (EGFR) and HER2, is effective in the treatment of some trastuzumab-resistant HER2-positive breast cancers in vitro and in vivo." (PMID 29156708, 2017). "Abolition of SRC kinases-mediated EGFR phosphorylation has been shown to inhibit EGF-induced proliferation and/or transformation in many types of cancer cells, such as breast cancer cells and cervical cancer cells." (PMID 26849234, 2016).
breast carcinoma (continued). "OA has previously been shown to activate the EGFR in a ligand-independent manner, and also to downregulate the expression of ERBB2 in breast cancer cells." (PMID 27894086, 2016). "Upon EGF induced phosphorylation PYK2 translocates to early endosomes and co‐localizes there with EGFR from where it enhances cell migration and potentiates epithelial‐to‐mesenchymal transition (EMT) in human breast carcinoma." (PMID 26506511, 2016). "It has been shown that ANO1 promotes cell proliferation and tumor growth in HNSCC and breast cancer by activating MAPK signaling pathway and activating EGFR and CAMK signaling respectively." (PMID 27732935, 2016). "When this study was nearing completion, we revealed that the enhanced phosphorylation of EGFR by NBD compounds is a result of the generation and action of hydrogen peroxide on the receptor in breast cancer cells." (PMID 27187356, 2016). "We evaluated a combination therapy co-targeting EGFR and PI3K in models of basal-like breast cancer in vitro and demonstrate synergistic anti-cancer effects that shrinks tumors in vivo, with greater efficacy than either monotherapy." (PMID 27484095, 2016). "The targets of the top luminal miRNAs were activators of EMT (ZEB1, ZEB2) and basal subtype transcription (IL-6, EGFR, STAT3), whereas the targets of the top basal miRNAs were involved in adipogenesis pathways and luminal breast cancer (ERBB2, ERBB3)." (PMID 27845906, 2016). "A positive correlation between AGO2 expression levels and the ERα− phenotype in breast cancer cell lines and tumor samples has been previously reported with AGO2 expression being regulated by EGFR/MAPK signaling." (PMID 29657266, 2016). "Autocrine WNT signaling contributes to breast cancer cell proliferation via the canonical WNT pathway and EGFR transactivation." (PMID 27487128, 2016). "Here we additionally examined the expression of HER1 (EGFR), HER3 and HER4 in the breast cancer samples by RT-qPCR." (PMID 27057311, 2016). "In our previous study, induction of microRNA-7 by trichostatin A (TSA) suppressed the off-target effect of lapatinib on EGFR up-regulation, thus overcome the metastatic ability of HER2-negative breast cancer cells." (PMID 27409165, 2016). "SOX10 suppression contributes to BRAF- and/or MEK-inhibitor resistance in BRAF mutated melanoma, by activating TGFβ signalling to upregulate EGFR and PDGFRB, whilst increasing SOX9 transcript abundance has been observed in breast cancer EMT." (PMID 27852308, 2016). "EGFR-specific binding peptide GE11 can guide Let-7a-containing exosomes to EGFR-positive cancer cells, which dramatically inhibited EGFR-positive human breast cancer cell growth in a xenograft mouse model." (PMID 28127287, 2016). "To characterize the expression of AXL in vitro, we analyzed the expression of the tyrosine kinase, EMT (CDH1 and VIM), and basal (EGFR, KRT5, and KRT6A) markers in 15 breast cancer cell lines by quantitative real-time PCR (qRT-PCR)." (PMID 28721387, 2016). "In support of our suggestion, a recent clinical trial demonstrates that the combinatorial treatment with an EGFR inhibitor and PTX improves the response of breast cancer patients to PTX." (PMID 26799187, 2016). "EGCG suppressed EGFR signaling and downstream phosphatidylinositol 3-kinase (PI3K)/Akt activation in the MCF-7 breast cancer cell line, resulting in down-regulation of FAS expression." (PMID 27483305, 2016). "In vitro, compared with mock-transduced NK-92 cells or primary NK cells, EGFR-CAR-engineered NK-92 cells and primary NK cells displayed enhanced cytotoxicity and IFN-γ production when co-cultured with breast cancer cell lines MDA-MB-231, MDA-MB-468, and MCF-7." (PMID 27050072, 2016). "Prolactin receptor (PRLR) and epidermal growth factor receptor (EGFR/ERBB1) have important roles in the physiology of the human breast and in the etiology and progression of breast cancer." (PMID 27564112, 2016).
breast carcinoma (continued). "And often, the status of ErbB receptor tyrosine kinase family, such as EGFR and HER2, dictates treatments for breast cancer patients." (PMID 27878106, 2016). "EGFR (ERBB1) immunohistochemistry and RT-qPCR showed a good overall concordance of 81% in breast cancer patients as described recently." (PMID 27610130, 2016). "Proliferation of MCF-7 breast cancer cells was activated by OA, most likely via transactivation of the EGFR, and OA was shown to downregulate ERBB2 in breast cancer cells." (PMID 27894086, 2016). "EGFR and HER-2 expression by immunohistochemistry (IHC) and their mRNA by in situ hybridization (ISH) in canine mammary carcinomas in mixed tumors and carcinosarcomas." (PMID 27490467, 2016). "The efficacies of anti-BCBMs of EGFR-CAR NK cells, oHSV-1, and their combination were tested in vitro and in a breast cancer intracranial mouse model." (PMID 27050072, 2016). "These important drug targets in breast cancer, ESR1, PGR, HER2, EGFR and AR have a high similarity in mRNA and protein variation in both tumors and cell lines." (PMID 27556158, 2016). "Several studies have investigated the clinical and functional roles of EGFRs (EGFR, HER2, HER3) and their downstream mediators (PTEN, PIK3CA, AKT, mTOR) in breast cancer BM." (PMID 26781299, 2016). "AGO2, a key component of miRNA induced gene silencing, is regulated by the EGFR/MAPK signaling cascade and high AGO2 expression levels in ERα− breast cancers have been reported." (PMID 29657266, 2016). "Among all the EGFR family members, EGFR and HER2 have been well studied and found to be co-regulated in breast cancer." (PMID 27736797, 2016). "Lapatinib, a TKI of EGFR and HER2 showed promising results in HER2 positive breast cancer previously." (PMID 27795701, 2016). "The EGFR is an important mediator of tumor development and progression, whereas IL-17E affects cell cycle progression, both in TNBC cells and in other breast cancer cells, such as human epidermal growth factor receptor 2 (HER2)-positive tumor cells." (PMID 27462789, 2016). "Combination treatment functionalized with both EGFR and HER2 antibodies towards breast cancer samples from patients also showed significantly higher anti-tumoral activity." (PMID 27213442, 2016). "Therefore, we examined whether it has an association between EGFR and breast cancer with ALNM risk or not." (PMID 27196477, 2016). "In Luminal B, F10 and EGFR genes from Luminal B pattern are also target genes of Menadione (repurposed drug from LINCS) and Lapatinib Breast cancer drug." (PMID 26892392, 2016). "The involvement of the modulation of EGFR and HER-2 signals in n-3 PUFAs-induced apoptosis has been reported by different studies, performed in different types of cancer (mainly breast cancer) cells." (PMID 26821053, 2016). "Suppression of AXL by an anti-tumor protein, E1A, enhanced EGFR-TKI (gefitinib, erlotinib and lapatinib) sensitization, resulting in significant inhibition of tumor growth in breast cancer cells." (PMID 27590506, 2016). "Given the emerging evidence for interaction between EGFR/ErbB2 and IGF/IRS signaling in breast cancer, we investigated crosstalk between ErbB2 and IRSs." (PMID 27765041, 2016). "Activation of alternative growth and survival signaling pathways, e.g. human epidermal growth factor receptor (HER1 or EGFR) and HER2, has been described in antiestrogen therapy-resistant breast cancer." (PMID 26849233, 2016). "Lapatinib led to downregulation of p-HER2 and p-EGFR, p-Akt and p-ERK, and increased radiosensitivity of breast cancer cells having overexpression of HER2." (PMID 27738326, 2016). "Summing these studies, it can be concluded that the re-expression of ERα in ER-negative breast cancer cells by inhibiting EGFR or Her-2 signalling restores, at least in part, a hormone-responsiveness and could be useful as a potential therapeutic approach to endocrine-resistant breast cancer." (PMID 27884978, 2016).
breast carcinoma (continued). "A study that combined treatment of bortezomib and Lapatinib, an inhibitor of epidermal growth factor receptor (EGFR) and HER2 tyrosine kinases, showed a synergistic effect in HER2-overexpressing breast cancer cells." (PMID 27655642, 2016). "Nevertheless, important drug targets in breast cancer, such as ESR1, PGR, HER2, EGFR and AR possess highly correlated in mRNA-protein expression both in tumors and cell lines." (PMID 27556158, 2016). "Human epidermal growth factor receptor 2 (HER2/ErbB2), a member of the epidermal growth factor receptor (EGFR) family, is overexpressed in several human cancers, including 20-25% of breast cancer (BC) cases and 10-30% of GC cases." (PMID 27167206, 2016). "EGFR/PI3K/AKT pathway plays a critical role in PD induced cell apoptosis and PD downregulates the expression of EGFR in MDA-MB-231 breast cancer cells subsequently leading to the inhibition of the PI3K/AKT and MAPK pathways." (PMID 28119606, 2016). "Our study showed that EGFR-CAR NK-92 cells can quickly target and attack breast cancer cells while oHSV-1 can slowly but constantly infect and destroy the cancer cells." (PMID 27050072, 2016). "Thus, we suggest that EGFR downregulation may not be associated with the DCA-induced metabolic shift in breast cancer cells." (PMID 27494858, 2016). "In line with clinical relevance of the EGFR–ERK–LIMT regulatory module, reduced expression of LIMT marks mammary tumors of patients diagnosed with relatively aggressive and advanced forms of the disease." (PMID 27485121, 2016). "Anxa2 expression was also positively correlated with the expression of epidermal growth factor receptor (EGFR) and epithelial–mesenchymal transition (EMT) markers in breast cancer tissues and cell lines." (PMID 26307676, 2015). "IGFBP-3-dependent breast cancer cell chemoresistance, while contrary to studies in some other cancers showing IGFBP-3-dependent chemosensitivity, might in part explain the association between high IGFBP-3 (and EGFR) expression and poor patient outcomes in women with ER-negative breast cancer." (PMID 26221601, 2015). "CUR has also been shown to (a) decrease the expression of phosphorylated forms of EGFR and ERK1/2; (b) induce apoptosis and cell cycle arrest; and (c) inhibit cell proliferation in the aggressive MDA-MB-231 breast cancer cell line in vitro." (PMID 25918934, 2015). "In conclusion, our study indicates that in combination, EGFR and CD44/CD24 expression status are powerful identifiers of breast cancer patient subgroups with different clinical behavior." (PMID 25429827, 2015). "Prior studies in ER+ breast cancer cell line models have shown that PELP1-cyto promotes activation of ERK1/2 and Akt signaling through EGFR to promote resistance to Tam." (PMID 25789479, 2015). "In breast cancer, the highly homologous miR-221 and miR-222 promote cell proliferation through the EGFR (epidermal growth factor receptor)-Ras-Raf-MAPK/ERK (mitogen-activated/extracellular signal-regulated protein kinase) pathway." (PMID 25797271, 2015). "Results showed that stable PTPH1 expression in T47D breast cancer cells decreases levels of endogenous and EGF-induced tyrosine phosphorylation of EGFR at Y1173 (p-EGFR/Y1173)." (PMID 26079946, 2015). "Subsequently, estrogen and tamoxifen were demonstrated to activate PI3Kinase in breast cancer cells and receptor-transfected COS-7 cells via GPER, also as a consequence of EGFR transactivation." (PMID 26470790, 2015). "Further understanding the contributions of the cross talk among the signaling pathways governed by EGFR, c-ABL, β-catenin, and HOTAIR is expected to shed new light to the diagnosis, treatment, and prognosis of breast cancer." (PMID 25883211, 2015). "Similar condition occurred after the treatment of other agents, such as gefitinib or iressa, a selective epidermal growth factor receptor TKI, primarily for NSCLC, also respond to breast cancer with positive HER‐2." (PMID 26305917, 2015).
breast carcinoma (continued). "The activation of the epidermal growth factor receptor (EGFR) signaling induces EMT in several types of carcinomas, including breast cancer." (PMID 26307676, 2015). "Five genes—CYP19A1, EGFR, ESR2, FOS, and IGF1—were common among all three EDCs–PCB 153, phthalates and BPA, breast cancer, and endometriosis." (PMID 26512648, 2015). "Lapatinib, a small-molecule TKI targeting the intracellular tyrosine kinase domain of EGFR and HER2, was found to improve time to progression in HER2 breast cancer patients who had progressed to tratuzumab." (PMID 26107737, 2015). "In this study we show that PYK2 integrates EGFR/HER2- and IL8-receptor signaling to potentiate cell invasion in breast cancer cells." (PMID 26084289, 2015). "Each has been reported to be amplified or overexpressed in some forms of breast cancer, with HER2 and EGFR being the most extensively studied." (PMID 26068969, 2015). "Lapatinib, a small molecule kinase inhibitor, blocks both EGFR and ERBB2 kinase activity and is currently used in combination therapy with DNA damaging agents in ERBB2-positive breast cancers." (PMID 25596742, 2015). "Lapatinib is a dual tyrosine kinase inhibitor of EGFR and ErbB2/HER2 receptors that is used in combination therapy of ErbB2/HER2-positive breast cancer patients with advanced or metastatic tumors." (PMID 25599599, 2015). "Other researchers found that nuclear EGFR cooperates with STAT3 to regulate iNOS expression, and its nuclear expression is positively correlated to iNOS expression, a prognostic marker for breast cancer." (PMID 26497368, 2015). "Fortunately, EGFR and HER2/neu trophic membrane receptors are both over-expressed in several resistant forms of breast cancer where their refractory response to chemotherapy is associated with an over-expression of transmembrane P-glycoprotein." (PMID 25821636, 2015). "Similar to EGFR, the vascular endothelial growth factor receptor (VEGFR) has been explored as a therapeutic target receptor in breast cancer." (PMID 25695063, 2015). "All three EDCs–PCB 153, phthalates, and BPA influenced five common genes—CYP19A1, EGFR, ESR2, FOS, and IGF1—in breast cancer as well as in endometriosis." (PMID 26512648, 2015). "In another breast cancer cell line, MDA-MB-231 (ER−/PR−/HER2−, EGFR+), a model for triple negative breast cancer, administration of 30 μM curcumin for 48 h reduced phosphorylation of ERK." (PMID 26694341, 2015). "Analysis of Gene Ontology associated with the significant TCS genes highlighted terms associated with metabolic processes and with the regulation of the EGFR/ERRB pathway, known to be very important in the biology of breast cancer." (PMID 26235388, 2015). "Following 5a treatment, two types of breast cancer cells (HER2-positive and EGFR-positive) were noticeably arrested in the G1 phase of the cell cycle, with a concomitant loss of the S- and G2/M-phase cell populations." (PMID 25766325, 2015). "Lapatinib, a small molecule inhibitor of the family of Human Epidermal Growth Factor Receptor 1 (HER1 or EGFR) and HER2 oncogenic receptor tyrosine kinases, is approved for the treatment of advanced stage HER2-overexpressing (HER2+) breast cancers." (PMID 26571496, 2015). "Lapatinib, a potent human epidermal growth factor receptor 2 (HER2) and epidermal growth factor receptor (EGFR) inhibitor, is an oral drug for breast cancer and other solid tumors." (PMID 26070816, 2015). "Other studies have previously identified overexpression of EGFR, and its ligand, amphiregulin (AREG), in young breast cancer patients." (PMID 26251034, 2015). "Although the majority of clinical benefits from lapatinib were achieved in patients with HER2-positive breast cancers, treatment with lapatinib for TNBC or HER2-negative patients continues to be of interest due to its anti-EGFR activity." (PMID 26513016, 2015).